DDX52 (DExD-box helicase 52)
Description:
Required for efficient ribosome biogenesis (By similarity). May control cell cycle progression by regulating translation of mRNAs that contain a terminal oligo pyrimidine (TOP) motif in their 5' UTRs, such as GTPBP4 (By similarity).
Synonyms: ROK1; HUSSY19
Tractability: Small molecule: a structure with a bound ligand is known. PROTAC: ubiquitination databases record sites on it; its protein half-life has been measured.
Gene: Protein-coding gene on chromosome 17 (37,609,739 to 37,643,446, reverse strand). Ensembl gene ENSG00000278053.
Subcellular location: Nucleus, nucleolus
Subcellular location (Human Protein Atlas): Nucleoli; Nucleoplasm
Pathways (Reactome):
Metabolism of RNA: Major pathway of rRNA processing in the nucleolus and cytosol; rRNA modification in the nucleus and cytosol
Gene Ontology:
Molecular function: RNA binding; ATP binding; ATP hydrolysis activity; nucleic acid binding; RNA helicase activity
Biological process: maturation of SSU-rRNA
Cellular component: membrane; nucleolus; nucleoplasm
Genetic constraint (gnomAD): Loss-of-function variants: 49 observed, 69.97 expected, observed/expected ratio (o/e) 0.7, 90% interval 0.56 to 0.89. The upper end of that interval is the gene's LOEUF score, 0.89, which puts it in group 3 of 6, group 1 being the genes least tolerant of losing a copy. Missense variants: 692 observed, 717.58 expected, observed/expected ratio (o/e) 0.96, 90% interval 0.9 to 1.03. Synonymous variants: 226 observed, 250.67 expected, observed/expected ratio (o/e) 0.9, 90% interval 0.81 to 1.01.
Homologues: Orthologues: chimpanzee DDX52 (99% identical), dog DDX52 (94% identical), pig DDX52 (92% identical), rabbit DDX52 (91% identical), guinea pig DDX52 (91% identical), macaque DDX52 (90% identical), mouse Ddx52 (88% identical), tropical clawed frog ddx52 (70% identical), zebrafish ddx52 (61% identical), Drosophila melanogaster ais (44% identical), Caenorhabditis elegans ddx-52 (38% identical). Paralogues in human: DDX43 (27% identical), DDX42 (26% identical), DDX4 (26% identical), DDX3X (25% identical), DDX3Y (25% identical), DDX53 (25% identical), DDX17 (25% identical), DDX59 (25% identical), DDX23 (24% identical), DDX5 (24% identical), DDX41 (23% identical), DDX46 (23% identical), and 26 more.
Diseases named in the same sentence as DDX52 in open-access papers:
DDX52 is named in the same sentence as 16 diseases in open-access papers, as found by Europe PMC text mining. Sharing a sentence is not in itself a finding about the gene and the disease. The quoted sentences say what the papers report.
lung carcinoma (2 papers, 2021 to 2023). "The ATP-dependent protein DEAD-box RNA helicase 52 (DDX52) is an important regulator in RNA biology and has been implicated in the development of prostate and lung cancer." (PMID 34233596, 2021). "Previous studies have shown that DDX52 expression is downregulated by activin-induced inhibition of the proliferation of prostate cancer cells and is associated with lung cancer; however, the clinical and biological functions of DDX52 in MM are unknown." (PMID 34233596, 2021). "Collectively, these intricate pathways likely interplay to orchestrate the regulatory mechanism of the DDX52 gene in the context of lung cancer." (PMID 37833424, 2023). "Moreover, qRT-PCR analysis of 8 paired lung cancer tissues and their corresponding normal lung tissues confirmed the increased expression of DDX52 in lung cancer tissues." (PMID 37833424, 2023). "DDX52 has been reported to be involved in prostate and lung cancer; however, the clinical and biological functions of DDX52 in MM are unknown." (PMID 34233596, 2021).
prostate carcinoma (2 papers, 2021). A carcinoma that arises from epithelial cells of the prostate gland. "DDX52 is a type of DEAD/H box RNA helicase that was identified as a novel prostate cancer (PCa) genetic locus and possible causal gene in a European large-scale transcriptome-wide association study." (PMID 34399732, 2021).
viral infections (2 papers, 2021 to 2022). "Moreover, DDX52 helicase was shown to regulate innate immunity against viral infections and enhance cellular processes to prevent viral replications." (PMID 35407693, 2022). "Some studies have shown that DDX52 is involved in the process of virus infection." (PMID 34399732, 2021).
diabetes (1 paper, 2016). "However, in the diabetes network, DDX52 only interacts with one direct neighbor." (PMID 27257970, 2016).
HIV-1 infection (1 paper, 2025). The type species of lentivirus and the etiologic agent of acquired immunodeficiency syndrome (AIDS). "In order to verify that the downregulation of DDX52 during HIV-1 infection is caused by the elevated expression of the microRNA, we analyzed the expression of DDX52 by silencing the microRNA during HIV-1 infection." (PMID 39826696, 2025). "Since DDX52 was downregulated during HIV-1 infection, we then wanted to determine the outcome of DDX52 overexpression on HIV-1 infection as well as on the expression of miR-197-3p." (PMID 39826696, 2025). "Our results also suggested that DDX52 and Vif physically interact with each other during HIV-1 infection." (PMID 39826696, 2025). "Enhanced ubiquitination of Vif in DDX52 overexpressed cells also prompted us to infer that Vif is regulated and degraded in the presence of DDX52 during HIV-1 infection." (PMID 39826696, 2025). "All our previous results have shown that HIV-1 infection leads to an increased expression of the microRNA miR-197-3p, leading to the downregulation of DDX52 and increased progeny virion infectivity." (PMID 39826696, 2025). "Subsequently, we were interested to examine whether DDX52 physically interacts with Vif during HIV-1 infection." (PMID 39826696, 2025). "Hence, it was crucial to first determine whether DDX52 expression has any correlation with A3G expression during HIV-1 infection." (PMID 39826696, 2025). "Moreover, the second best target was DDX52, a DEAD box RNA helicase, whose function is uncharacterized with respect to HIV-1 infection." (PMID 39826696, 2025). "Interestingly, qRT-PCR analysis showed no change in the expression of vif mRNA upon overexpression of DDX52 during HIV-1 infection, indicating that DDX52 expression has a negative impact on HIV-1 Vif expression at the protein level alone." (PMID 39826696, 2025). "Interestingly, DDX52, a target of miR-197-3p, showed a negative impact on virion infectivity during HIV-1 infection." (PMID 39826696, 2025).
melanoma (1 paper, 2021). A malignant, usually aggressive tumor composed of atypical, neoplastic melanocytes. "The present study provides new insights into DDX52 function in human melanoma tissues." (PMID 34233596, 2021). "To prove this hypothesis, we detected the expression of DDX52 in human melanoma tissues and evaluated its effects on melanoma cell growth in vivo and in vitro." (PMID 34233596, 2021).
metastatic melanoma (1 paper, 2026). A melanoma that has spread from its primary site to another anatomic site. "DDX52 is essential for cell survival and is an emerging biomarker for the onset of metastatic melanoma." (PMID 41510705, 2026).
tumor (4 papers, 2021 to 2023). "The DDX52 gene, encoding an RNA helicase, is acclaimed for its vital role in numerous biological processes, encompassing tumor growth, cell differentiation, ribosome biogenesis, and spermatogenesis." (PMID 37833424, 2023). "In summary, the multifarious influence of the DDX52 gene on tumor growth, cell differentiation, ribosome biogenesis, and spermatogenesis warrants thorough investigation." (PMID 37833424, 2023). "We used a tumor xenograft model to examine the mechanism by which downregulation of DDX52 inhibits MM cell proliferation." (PMID 34233596, 2021). "Together, these results suggest that downregulation of DDX52 suppresses tumor growth and tumorigenicity by regulating c-Myc expression." (PMID 34233596, 2021). "Notably, elevated expression of the DDX52 gene shows a positive correlation with T and N stages, exhibiting a concurrent increase with tumor stage and grade." (PMID 37833424, 2023). "Knockdown of DDX52 significantly suppressed tumor growth and size." (PMID 34233596, 2021). "Targeting DDX52 could be a feasible strategy for inhibiting c-Myc-driven PCa tumor growth." (PMID 34399732, 2021). "DDX52 is a type of DEAD/H box RNA helicase, and its suppression exerts an anti-tumor effect." (PMID 36313471, 2022).
cancer (3 papers, 2017 to 2026). A tumor composed of atypical neoplastic, often pleomorphic cells that invade other tissues. "Collectively, these findings underscore the therapeutic potential of targeting the DDX52 gene not only for LUAD but also for diverse cancers." (PMID 37833424, 2023). "Broadening our perspective to pan-cancer data, we examined the DDX52 gene’s expression across various cancers." (PMID 37833424, 2023). "Moreover, our pan-cancer investigation highlights the aberrant elevation of the DDX52 gene across various other cancer types." (PMID 37833424, 2023). "Beyond its implications in cancer, DDX52 plays a crucial role in spermatogenesis." (PMID 37833424, 2023). "Consequently, the DDX52 gene emerges as a potential therapeutic and prognostic marker, with substantial implications for cancer diagnosis and treatment." (PMID 37833424, 2023). "Using CRISPR-Cas9 genetic editing, we generated U2OS cell lines heterozygous for DDX52 (DDX52+/-), which exhibit growth defects and impaired cell migration, providing direct support for previous suggestions that DDX52 may promote cancer cell metastasis and C-myc regulation." (PMID 41510705, 2026). "The outcomes revealed substantial enrichment of the DDX52 gene across various pathways, notably the cell cycle, DNA replication, ERBB, MAPK, mTOR, cancer pathways, TGF-beta, and Wnt." (PMID 37833424, 2023).
adenocarcinoma (1 paper, 2023). A common cancer characterized by the presence of malignant glandular cells. "Similarly, in the TCGA LUAD dataset, a comparison between paired adenocarcinoma lung samples and normal lung tissue samples revealed a notable upregulation of DDX52 gene expression in the adenocarcinoma samples." (PMID 37833424, 2023).
infection (1 paper, 2025). The state of being infected such as from the introduction of a foreign agent such as serum, vaccine, antigenic substance or organism. "Immunoprecipitations using A3G and/or DDX52 antibodies followed by immunoblotting with respective antibodies demonstrated the interaction of these two proteins during infection." (PMID 39826696, 2025). "Our results in Jurkat J6 cells indicated that with infection progression, there was a decrease in the expression of DDX52 with gradual increase in Vif expression." (PMID 39826696, 2025). "Our results demonstrated that with knockdown of miR-197-3p, the expression of DDX52 increased at the peak of infection, both at mRNA and protein levels." (PMID 39826696, 2025).
DDX52 also shares sentences with these, for which no sentence is quoted: dentatorubral-pallidoluysian atrophy (1 paper); heart failure (1); metabolic syndrome (1); metastatic tumors (1); Wilson disease (1).